IDH2 (isocitrate dehydrogenase (NADP(+)) 2)
Diseases named in the same sentence as IDH2 in open-access papers (continued):
Sharing a sentence is not in itself a finding about the gene and the disease.
oligodendroglioma (continued). "Isocitrate dehydrogenase (IDH) is another TCA cycle enzyme that converts isocitrate to alpha-ketoglutarate, and IDH1/IDH2 mutations have been reported in a number of cancers including leukemia, melanomas, oligodendrogliomas, and astrocytomas." (PMID 33804114, 2021). "Oligodendroglioma is characterised by either IDH1 or IDH2 mutations combined with the loss of both 1p/19q chromosomal arms." (PMID 33477674, 2021). "In contrast, the overall prevalence of IDH2 mutation was 1%, being most frequent in anaplastic oligodendrogliomas, oligodendrogliomas and cutaneous squamous cell carcinomas (<15%)." (PMID 35996504, 2021). "Of the genes already associated with the development of oligodendroglioma (IDH1/IDH2, CIC, and FUBP1), remarkably only the mutation in IDH1 (NM_005896:c.395G>A) was present in the primary O2005." (PMID 31217899, 2019). "The presence of an IDH1 or IDH2 mutation is also required for the diagnosis of oligodendroglioma and anaplastic oligodendroglioma." (PMID 29098416, 2018). "IDH1 and IDH2 genes mutations play a prominent role in gliomagenesis, specific to both oligodendrogliomas and astrocytomas." (PMID 29099032, 2017). "More than 70 % of Stage II–III astrocytoma or oligodendroglioma tumors have mutations in either IDH1 or IDH2." (PMID 23229761, 2013). "The diagnosis of diffuse astrocytoma or oligodendroglioma (grade 2–3), traditionally based solely on histomorphological criteria, now requires the demonstration of the presence of the IDH1 or IDH2 mutation and, in the case of oligodendrogliomas, of the 1p/19q codeletion." (PMID 41517303, 2025). "In addition, 1p/19q codeletion and IDH1 or IDH2 mutation are typical molecular features in oligodendroglioma." (PMID 35372027, 2022). "Interestingly, IDH2 mutations are mainly found in oligodendrogliomas, while IDH1 mutations differing from R132H are mostly seen in astrocytomas." (PMID 33081358, 2020). "This novel classification system incorporates mutations in the isocitrate deshydrogenase 1 and 2 genes (IDH1 and IDH2) and the whole-arm chromosomal loss of 1p and 19q (1p/19q-codeletion), which are both required to be present for confirming the diagnosis of oligodendroglioma." (PMID 30193580, 2018). "However, we found here that IDH1nonR132H mutations are associated with astrocytic tumors, whereas IDH2 mutations are associated with oligodendrogliomas." (PMID 24877111, 2014). "Specifically, the label defined its indication for patients with IDH1- or IDH2-mutant astrocytoma or oligodendroglioma following surgery." (PMID 40867259, 2025). "In oligodendrogliomas, IDH1 gene mutations are strongly associated with dysfunctions of cellular cytosol and peroxisomes, while IDH2 mutations are only detectable in a small number of oligodendrogliomas that do not carry IDH1 mutations." (PMID 40426960, 2025). "Vorasidenib, an IDH-1 and IDH-2 inhibitor improved the progression free survival (27.7 months vs. 11.1 months) compared to placebo in patients with residual or recurrent grade 2 oligodendroglioma or astrocytoma in a phase III trial." (PMID 41567539, 2025). "Historically they were defined by histopathological features, but the 2021 WHO diagnostic criteria defined oligodendroglioma by molecular markers, specifically the co-occurrence of an IDH1 or IDH2 mutation and a 1p/19q codeletion." (PMID 41375081, 2025). "The most recent case in 2020 involved multiple bone and bone marrow metastases from a 1p/19q-codeleted and IDH2-mutant oligodendroglioma, WHO grade 3, confirmed by MLPA studies." (PMID 39061087, 2024). "Mutations in IDH1 or IDH2 are disease-defining features of IDH-mutant and 1p/19q co-deleted oligodendroglioma and IDH-mutant astrocytoma." (PMID 37919784, 2023). "For instance, in IDH1 or IDH2 mutant human oligodendrogliomas, distinct CNV sub-clones displayed similar cellular hierarchies, suggesting that the cell states were primarily dictated by developmental programs." (PMID 34405376, 2022).
oligodendroglioma (continued). "All 45 cases of oligodendroglioma showing 1p/19q codeletion also presented with an IDH gene mutation (40/45 IDH1-R132H, 1/45 IDH1-R132L, 4/45 IDH2)." (PMID 34020723, 2021). "Mutations in IDH1, or less frequently IDH2, define two major classes of malignant gliomas: astrocytoma (IDH-A) and oligodendroglioma (IDH-O)." (PMID 34948008, 2021). "And most oligodendrogliomas with 1p/19q co-deleted, which indicates poor prognosis, are accompanied by IDH1 and IDH2 mutation." (PMID 34722274, 2021). "In oligodendrogliomas, haploinsufficiency occurs with a high frequency in the context of an IDH1/IDH2 variant." (PMID 31217899, 2019). "TCF12 mutations occurred only among oligodendrogliomas 1p19q codeleted with TERT promoter mutations and with IDH1 or IDH2 mutations (particularly frequent among IDH2-mutated tumors)." (PMID 30279357, 2018). "In conclusion, the oligodendrogliomas can be defined, independently of their histopathological features, by the presence of both an IDH1 or IDH2 mutation and codeletion of chromosome arms 19 and 19q." (PMID 30279357, 2018). "Large-scale sequencing studies revealed that heterozygous mutations in both cytosolic IDH1 and mitochondrial IDH2 are highly prevalent in World Health Organization (WHO) grade II and III astrocytomas or oligodendrogliomas and in secondary glioblastomas." (PMID 29567975, 2018). "Further investigations have shown that mutations in IDH1 and IDH2 are present in high proportions of grade II and III astrocytic and oligodendroglial tumours (72–100%) along with secondary GBMs (85%), but are largely absent in primary GBMs (5%)." (PMID 25147764, 2014). "The majority of oligodendrogliomas (ODGs) exhibit combined losses of chromosomes 1p and 19q and mutations of isocitrate dehydrogenase (IDH1-R132H or IDH2-R172K)." (PMID 25277207, 2014). "We analyzed a cohort of 17 oligodendroglial tumor samples, consisting of nine cases diagnosed as oligodendroglioma (O) and eight as oligoastrocytoma (OA) for copy number variations (CNV); CIC, FUBP1 and IDH1/IDH2 mutations; and gene expression changes." (PMID 24086756, 2013). "IDH-mutant and 1p/19q-co-deleted oligodendrogliomas are the second tumor classified as diffuse lower-grade adult glioma and are characterized by the coexistence of an IDH1 or IDH2 mutation and the deletion of the entire 1p and 19q arms, as well as a characteristic morphological appearance." (PMID 41517303, 2025). "Similar to IDH-mutant astrocytomas, IDH1 R132H represents the most common mutation in oligodendrogliomas, although non-canonical mutations in IDH2 at codon 172 are more common in oligodendrogliomas compared to astrocytomas." (PMID 37239289, 2023). "The majority (90%) of astrocytomas and oligodendrogliomas carry a canonical IDH1 R132H mutation, which can be detected by IDH1 (R132H), while other mutations should be detected through the sequencing involving IDH1 and IDH2 genes." (PMID 35991838, 2022). "In contrast, loss of H3K27me3 was never seen in IDH1-R132L or IDH2-mutated 1p/19q codeleted oligodendrogliomas." (PMID 34020723, 2021). "IDH1 and IDH2 mutations are generally detected in astrocytoma and oligodendroglioma but not in the GBM subtype." (PMID 31803734, 2019). "Three out of four oligodendrogliomas and one oligoastrocytoma were all mutated at codon 132 of IDH1 whereas one oligodendroglioma did not harbor mutations at the canonical codons 132 or 172 of IDH1 or IDH2." (PMID 24349039, 2013). "Interestingly, in non-canonical IDH1-mutated (IDH1-R132L) or IDH2-mutated (IDH2-R172K, IDH2-R172W, IDH2-R172S) oligodendrogliomas with 1p/19q codeletion, loss of H3K27me3 was never observed." (PMID 34020723, 2021).
oligodendroglioma (continued). "The work published by Tirosh I. and colleagues documented different gene expression profile signatures of 4347 single cells on oligodendrogliomas, showing the classical IDH1/IDH2 dualism." (PMID 37510235, 2023). "Of particular note, IDH2-mutant tumors were localized within the expression space of oligodendrogliomas, indicating a distinct expression profile from that of IDH1-mutant oligodendrogliomas." (PMID 32732999, 2020). "However, all IDH2 Mut oligodendrogliomas showed retained H3K27me3 staining, indicating a differential methylation status between IDH1 and IDH2 Mut groups (P ≤ 0.05)." (PMID 34020723, 2021). "Four oligodendrogliomas with 1p/19q codeletion and typical oligodendroglial histology were designated to NOS group since IDH1/IDH2 mutation could not be detected." (PMID 28467778, 2017). "Four oligodendrogliomas in our cohort with 1p/19q codeletion and typical oligodendroglial histology were designated to NOS group since no IDH1/IDH2 mutation could be detected." (PMID 28467778, 2017). "However, H3K27me3 staining was always present in non-canonical IDH1/IDH2 Mut oligodendrogliomas." (PMID 34020723, 2021).
chondrosarcoma (95 papers, 2012 to 2026). A malignant cartilaginous matrix-producing mesenchymal neoplasm arising from the bone and soft tissue. "Research on detecting IDH2 mutations in plasma from patients with chondrosarcoma, osteosarcoma, and Ewing Sarcoma is currently limited." (PMID 40288045, 2025). "When the authors compare the present data to analysis performed in tumor samples an average of 12.1 % of IDH2 mutations have been described in chondrosarcoma tumor cases, being higher among grade III when compared to Grade II." (PMID 40288045, 2025). "The researchers analyzed plasma samples from patients and identified mutations in the IDH2 gene, with a frequency of approximately 10 %,26 just slightly lower than what the authors found (n = 1/8; 12.5 % of chondrosarcoma cases)." (PMID 40288045, 2025). "Patient 1, despite multiple surgeries for chondrosarcoma, exhibited a progressive disease course with recurrent local tumors and lung metastases, correlating with the presence of the IDH2 mutation." (PMID 40288045, 2025). "Driver mutations in IDH1 and IDH2 are initiating events in the evolution of chondrosarcoma and several other cancer types." (PMID 41299743, 2025). "This is commensurate with the literature, as it is known that chondrosarcomas are affected more often by IDH1 mutations than IDH2." (PMID 38254737, 2024). "IDH1 and IDH2 mutations occur in approximately 50–75% of chondrosarcoma cases, with the prevalence varying by tumor subtype." (PMID 39684713, 2024). "Mutations in genes such as IDH1 and IDH2, which are involved in cellular metabolism, have been frequently observed in both skeletal and extraskeletal chondrosarcomas." (PMID 39717304, 2024). "Other retrospective studies reported IDH mutations (mainly IDH1 R132 followed by IDH2 R172) in 34% to 67% of patients with chondrosarcomas, more frequently in high-grade than in low-grade chondrosarcomas." (PMID 38170705, 2024). "IDH1 and IDH2 mutations play a significant role in the progression and molecular characteristics of chondrosarcomas, as identified in recent multi-omics studies." (PMID 39590345, 2024). "To confirm the role of ER stress in vivo, we established a patient-derived xenografts mouse model from a high-grade chondrosarcoma with IDH2 (H172R) mutation." (PMID 38267611, 2024). "IDH2 mutations are seen in 8.6% of chondrosarcomas, most of them being an R172S transversion (AGG N AGT)." (PMID 38236556, 2024). "IDH2 mutations are extremely diffused in dedifferentiated chondrosarcomas, helping the differential diagnosis from osteosarcoma." (PMID 39123479, 2024). "Genetically, the frequent mutations such as IDH1 and IDH2 observed in chondrosarcoma were also present in benign tumour and therefore provided limited information to guide clinical decision making." (PMID 38267611, 2024). "Most importantly, a differential analysis of methylation patterns revealed a decrease in the global hypermethylation typically associated with IDH1/IDH2 in conventional chondrosarcoma." (PMID 37568740, 2023). "Isocitrate dehydrogenase 1/isocitrate dehydrogenase 2 (IDH1/IDH2) mutations were present in 36% conventional chondrosarcomas and 71% DDCS." (PMID 36926116, 2023). "Differential methylation analysis revealed reduction of IDH1/IDH2-associated global hypermethylation characteristically seen in conventional chondrosarcoma and a distinct methylation profile in DDCS." (PMID 36926116, 2023). "According to the primary diagnosis in this cohort, we also detected H3F3A in giant cell tumor of bone and malignant giant cell tumor of bone, IDH1/IDH2 mutations in chondrosarcoma, and NCOA2 fusion in mesenchymal chondrosarcoma." (PMID 35756627, 2022).
chondrosarcoma (continued). "Somatic gain-of-function variants in IDH1 and IDH2 have been described in the enchondromas, vascular anomalies and chondrosarcomas of approximately 80% of the individuals with OD and MS." (PMID 36480544, 2022). "A recent study showed that the OS of chondrosarcoma patients with IDH2 mutation was significantly shorter than that of patients without mutation." (PMID 33981605, 2021). "Specifically, mutations in IDH1 or IDH2 isoforms are identified in approximately 60% of chondrosarcomas." (PMID 34938658, 2021). "38-79% of chondrosarcomas have IDH1/IDH2 mutations with an enzymatic neomorphic activity and they use NADPH or NADH as a cofactor." (PMID 34938658, 2021). "The frequency of IDH2 mutations in dedifferentiated chondrosarcoma is much higher than that of other chondrosarcomas." (PMID 33981605, 2021). "IDH2 mutation solely occurred at codon 172 in chondrosarcomas with R172S being the most frequent IDH2 genotype." (PMID 34085407, 2021). "IDH2 mutations in chondrosarcoma cells are known to modulate mesenchymal differentiation through epigenetic dysregulation and treatment with the hypomethylating agent 5-azacytidine is a promising therapeutic strategy." (PMID 34938658, 2021). "Overall, mutations in IDH1/IDH2 or EXT1/EXT2 have been shown to have a role in the pathogenesis of most common central or peripheral chondrosarcomas, respectively." (PMID 32295254, 2020). "Mutations in the isocitrate dehydrogenase (IDH1 or IDH2) genes are common in enchondromas and chondrosarcomas, and lead to elevated levels of the oncometabolite D-2-hydroxyglutarate causing widespread changes in the epigenetic landscape of these tumors." (PMID 33266275, 2020). "Concurrent IDH1 and IDH2 mutations have been reported in two AMLs,5 four anaplastic gliomas, and three chondrosarcomas." (PMID 32333643, 2020). "Central conventional chondrosarcomas harbor specific point mutations in isocitrate dehydrogenase 1 or -2 (IDH1 or IDH2) in ~50% of the cases." (PMID 31810230, 2019). "Central chondrosarcomas carry mutations in the genes encoding the enzymes isocitrate dehydrogenase 1 or -2 (IDH1 or IDH2) in approximately 50% of cases, resulting in production of the oncometabolite d-2-hydroxyglutarate (D-2HG)." (PMID 31160965, 2019). "Compared to IDH1/2 wildtype cell lines, chondrosarcoma cell lines harboring an endogenous IDH1 (n=3) or IDH2 mutation (n=2) showed up to a 100-fold increase in intracellular and extracellular D-2-HG levels." (PMID 25895133, 2015). "Central conventional chondrosarcomas carry mutations in IDH1 or IDH2 in 38–70% of primary central chondrosarcomas (arising without a preexisting benign enchondroma) and in 86% of the secondary central chondrosarcomas." (PMID 26046462, 2015). "In further support of this concept, we observed a decrease in D-2HG levels in post-resection blood and urine samples of a patient with IDH2 R172S mutated dedifferentiated chondrosarcoma." (PMID 26368816, 2015). "Although IDH1/IDH2 mutations appear to be an important genetic event in the pathogenesis of enchondromas and central chondrosarcomas, other mutations are likely to exert an impact on the biological behaviour of the disease." (PMID 25432631, 2015). "This study demonstrated that osteosarcoma possesses IDH2 mutations, especially IDH2-R172S, which is also frequently observed with chondrosarcoma, which is another primary malignant bone tumor." (PMID 24403254, 2013). "We show here the use of L2975 dedifferentiated chondrosarcoma cells with an IDH2 R172W mutation in mouse models, which can be an important asset in the research for new treatment strategies." (PMID 22928481, 2012). "Recently IDH1 and IDH2 mutations were found in conventional central and dedifferentiated chondrosarcomas." (PMID 22928481, 2012).